RTBDN (retbindin)
Description:
Riboflavin-binding protein which might have a role in retinal flavin transport.
Synonyms: FLJ36353
Tractability: Antibody: UniProt places it where antibodies can reach, with medium confidence; UniProt predicts a signal peptide or a membrane-spanning region; its Gene Ontology location is reachable by antibodies, with medium confidence.
Gene: Protein-coding gene on chromosome 19 (12,825,477 to 12,838,362, reverse strand). Ensembl gene ENSG00000132026.
Subcellular location: Secreted, extracellular space, extracellular matrix, interphotoreceptor matrix; Cell membrane
Subcellular location (Human Protein Atlas): Endoplasmic reticulum; Predicted to be secreted
Gene Ontology:
Molecular function: riboflavin binding; riboflavin transmembrane transporter activity; signaling receptor activity
Biological process: riboflavin transport
Cellular component: plasma membrane; interphotoreceptor matrix
Genetic constraint (gnomAD): Loss-of-function variants: 22 observed, 19.46 expected, observed/expected ratio (o/e) 1.13, 90% interval 0.81 to 1.61. The upper end of that interval is the gene's LOEUF score, 1.61, which puts it in group 6 of 6, group 1 being the genes least tolerant of losing a copy. Missense variants: 320 observed, 308.74 expected, observed/expected ratio (o/e) 1.04, 90% interval 0.94 to 1.14. Synonymous variants: 140 observed, 127.02 expected, observed/expected ratio (o/e) 1.1, 90% interval 0.96 to 1.27.
Homologues: Orthologues: chimpanzee RTBDN (99% identical), macaque RTBDN (95% identical), pig RTBDN (70% identical), dog RTBDN (69% identical), rat Rtbdn (59% identical), guinea pig RTBDN (56% identical), mouse Rtbdn (55% identical), zebrafish rtbdn (27% identical), tropical clawed frog rtbdn (21% identical). Paralogues in human: FOLR3 (18% identical), FOLR1 (17% identical), FOLR2 (17% identical), IZUMO1R (17% identical).
Diseases named in the same sentence as RTBDN in open-access papers:
RTBDN is named in the same sentence as 9 diseases in open-access papers, as found by Europe PMC text mining. Sharing a sentence is not in itself a finding about the gene and the disease. The quoted sentences say what the papers report.
retinal degeneration (2 papers, 2020 to 2025). Degeneration of the retina. "We found that RF deficiency caused the downregulation of retinal flavins, RTBDN levels, and gradually led to functional decline, retinal degeneration, changes in the RPE and abnormalities in retinal metabolic activity." (PMID 40684659, 2025). "Our previous study identified RTBDN as a retinal-specific RF binding protein, which helps maintain retinal flavin levels and plays a protective role in various retinal degeneration models." (PMID 40684659, 2025). "Our previous research demonstrated that ablation of RTBDN, a retina-specific riboflavin binding protein, plays a pivotal role in maintaining flavin levels, leading to progressive retinal degeneration." (PMID 40684659, 2025). "We look forward to future studies evaluating potential specific functions for RTBDN and further exploration into the role of flavins and flavin-metabolism on retinal degeneration." (PMID 33138244, 2020). "The mechanisms by which removal of RTBDN worsens retinal degeneration and the precise function of RTBDN remain unclear." (PMID 33138244, 2020). "Overall, these findings suggest that RTBDN may play a protective role during retinal degenerations that occur at varying rates and due to varying disease mechanisms." (PMID 33138244, 2020). "Here, we utilize two different models of inherited retinal degeneration, the rhodopsin P23H knockin (RhoP23H/+) model of RP and the Prph2 Y141C knockin (Prph2Y141C/+) model of cone-rod dystrophy to evaluate whether eliminating retbindin has broad effects on retinal degeneration." (PMID 33138244, 2020).
lung carcinoma (1 paper, 2025). "The lactate-related risk score, constructed using ADAMTS3, FADS2, and RTBDN, was further explored to assess their expression and prognostic value for radiotherapy patients with lung cancer across multiple databases." (PMID 40861806, 2025). "The increased methylation of ADAMTS3, FADS2 and RTBDN was found in lung cancer tissues, potentially contributing to their downregulation." (PMID 40861806, 2025).
Macular dystrophy (1 paper, 2020). Macular dystrophy is a nonspecific term for retinal degeneration, generally confined to the macula, usually presumed of genetic origin. "We found that eliminating Rtbdn in the R172W Prph2 model of macular dystrophy exacerbated Prph2-associated retinal disease, suggesting RTBDN may play a protective role in IRD." (PMID 33138244, 2020).
Riboflavin deficiency (1 paper, 2025). "An intriguing finding in this study is the biphasic response of RTBDN to early ariboflavinosis." (PMID 40684659, 2025). "In the nutritional model of adult-onset ariboflavinosis, where mice were fed RDC starting at P30, we found that RTBDN levels were reduced as long as the mice remained on the RDC diet, but these levels were restored upon RF supplementation." (PMID 40684659, 2025).
cancer (1 paper, 2025). A tumor composed of atypical neoplastic, often pleomorphic cells that invade other tissues. "Given the role of aberrant DNA methylation in cancer-related dysregulation, the UALCAN database was utilized to investigate the relationship between the expression patterns of ADAMTS3, FADS2, and RTBDN and methylation levels in both normal and tumor tissues." (PMID 40861806, 2025).
tumor (1 paper, 2025). "ADAMTS3 and FADS2 exhibited downregulation in tumor tissues compared to normal lung tissues, whereas RTBDN displayed an opposite trend." (PMID 40861806, 2025).
RTBDN also shares sentences with these, for which no sentence is quoted: cone-rod dystrophy (1 paper); retinal disease (1); retinitis pigmentosa (1).